CCR6 (C-C motif chemokine receptor 6)
Diseases named in the same sentence as CCR6 in open-access papers (continued):
Sharing a sentence is not in itself a finding about the gene and the disease.
colorectal cancer (31 papers, 2011 to 2026). A primary or metastatic malignant neoplasm that affects the colon or rectum. "CCL-20 promotes colitis-associated colorectal cancer by recruiting CC-chemokine-receptor-6 (CCR-6)-expressing B cells and γδ T cells through chemotaxis." (PMID 34574641, 2021). "The chemokine receptor CCR6 was reported as a prognostic marker in colorectal cancer because the up-regulation of CCR6 has been associated with colorectal cancer metastasis." (PMID 30020984, 2018). "The chemokine receptor CCR6 has been recently shown to be associated with colorectal cancer (CRC) progression." (PMID 24979261, 2014). "Immunohistochemical analysis of 64 colorectal cancer cases found that the expression of CCR6 is closely associated with the hepatic metastasis of colorectal cancer, prompting that CCR6 and its ligands are involved in this process." (PMID 24743888, 2014). "CCR6 is significantly up-regulated in both colorectal cancer and associated liver metastases and data suggests that it plays a role in the recruitment of CCR6+ tumour cells to the site of distant metastases." (PMID 21249124, 2011). "CCR6 has also been implicated in CCR6-mediated angiogenesis in colorectal cancer." (PMID 35770088, 2022). "Interactions between the inflammatory chemokine CCL20 and its receptor CCR6 have been associated with colorectal cancer growth and metastasis, however, a causal role for CCL20 signaling through CCR6 in promoting intestinal carcinogenesis has not been demonstrated in vivo." (PMID 24866282, 2014). "CCL20 signaling through CCR6 caused increased production of CCL20 by colorectal cancer cell lines." (PMID 24866282, 2014). "Recently, it has been reported that the CCL20/CCR6 axis is implicated in HCC progression, colorectal cancer and pancreatic cancer." (PMID 40115013, 2025). "CCL20/CCR6 was shown to promote the growth of colorectal cancer through ERK phosphorylation in some studies." (PMID 36447119, 2023). "Expression of the C-C chemokine CCL20, also known as macrophage inflammatory protein-3 α (MIP-3 α) and liver activation regulated chemokine (LARC), as well as its receptor CCR6 have been observed in several malignancies including colorectal cancer." (PMID 34853656, 2021). "In particular, CCL20 acting on CCR6 expressed by colorectal cancer neoplastic epithelial cells induces proliferation, migration, and initiates an auto-feedback loop by inducing further secretion of CCL20." (PMID 34853656, 2021). "Reference 89 to “Liu, J.; Ke, F.; Xu, Z.; Liu, Z.; Zhang, L.; Yan, S.; Wang, Z.; Wang, H.; Wang, H. CCR6 is a prognostic marker for overall survival in patients with colorectal cancer, and its overexpression enhances metastasis in vivo." (PMID 31146450, 2019). "The correct reference is “Liu, J.; Ke, F.; Xu, Z.; Liu, Z.; Zhang, L.; Yan, S.; Wang, Z.; Wang, H.; Wang, H. CCR6 is a prognostic marker for overall survival in patients with colorectal cancer, and its overexpression enhances metastasis in vivo." (PMID 31146450, 2019). "The expression of CCL20 and CCR6 has been documented in several tumor types including colorectal cancer." (PMID 24866282, 2014). "We injected mouse CMT93 colorectal cancer cells s.c. into CCR6−/− mice to exclude the effect of CCR6 expressed by other immune cells in hosts." (PMID 24979261, 2014). "To assess for an association of CCL20 and its receptor CCR6 with colorectal cancer, we evaluated the expression of CCL20 and CCR6 in human tumors." (PMID 24866282, 2014). "A possible role of CCL20 in the liver mediating metastasis of CCR6-expressing colorectal cancer cells has been explored." (PMID 24866282, 2014). "Recently, involvement of the chemokine/receptor system CCL20/CCR6 in colorectal cancer (CRC) progression was shown." (PMID 24559209, 2014). "The chemokine receptor CCR6 is expressed in colorectal cancer and stimulation by the chemokine ligand CCL20 promotes proliferation of colorectal cancer cells." (PMID 24259307, 2013).
colorectal cancer (continued). "One study in colorectal cancer has demonstrated that tumour associated macrophages secrete CCL20 and are responsible for the recruitment of CCR6+ regulatory T cells which enhance tumour development." (PMID 23469070, 2013). "In sporadic colorectal cancer, CCL20/CCR6 signaling has been shown to play a role in the proliferation and migration of colorectal cancer cells and in the promotion of liver metastasis via the autocrine and paracrine functions." (PMID 24179507, 2013). "Moreover, CCL20/CCR6 apparently­ plays a role in organ selective liver metastasis of colorectal cancer." (PMID 30603057, 2018). "Furthermore, a recent study has reported that tumour-associated macrophages (TAMs) can produce CCL20, resulting in increased recruitment of CCR6+ regulatory T cells, and promote colorectal cancer development in mice." (PMID 28798316, 2017). "Moreover, this is strongly supported by a previous study demonstrating that even colonic MAIT cells displayed high expression of CCR6 in patients with colorectal cancer." (PMID 27517754, 2016). "Moreover, CCL20, the ligand for CCR6, has been known to be highly expressed in gastric cancer, colorectal cancer, and lung cancer." (PMID 27517754, 2016). "The chemokine receptor CCR6 is of particular interest in the liver metastasis of colorectal cancer." (PMID 24979261, 2014). "Expression of CCL20 and CCR6 has been observed in several malignancies including colorectal cancer." (PMID 24866282, 2014). "CCR6-dependent ERK phosphorylation mediated proliferation of colorectal cancer cells." (PMID 21949768, 2011). "In order to determine whether signaling through CCR6 causes production of CCL20, we used ELISA to assay levels of CCL20 in the supernatant of MC38 murine colorectal cancer cells and splenocytes isolated either from wild-type or CCR6KO mice upon stimulation with CCL20." (PMID 24866282, 2014). "For example, CCL20, by binding to CCR6, regulates the ability of cells to migrate and invade by activating the RhoA pathway in colorectal cancer, a role not commonly seen in other chemokines." (PMID 38791448, 2024).
hepatocellular carcinoma (27 papers, 2008 to 2025). A malignant tumor that arises from hepatocytes. "LARC(CCL20) and his sole receptor CCR6 will favour migration of Treg cells into a tumour microenvironment and disease progression in hepatocellular carcinoma." (PMID 35108275, 2022). "Hepatocellular carcinoma (HCC) cells promote the chemoattraction of CCR6+ B lymphocytes by secreting CCL20 and facilitate cancer development by enhancing angiogenesis." (PMID 35841069, 2022). "These include evaluation of the CXCL12/CXCR4 axis in angiogenesis, the CCL20/CCR6 axis in the growth of the hepatoma cell line Huh7; and the CCL5/CCR1 axis in promoting the metastasis and invasion of HCC cells." (PMID 32260550, 2020). "Stimulation by CCL20 upregulated the mRNA level of CCR6 in hepatocellular carcinoma cells." (PMID 32418112, 2020). "In our present study, we aimed to clarify whether CCR6/CCL20 was correlated with the migration of hepatocellular carcinoma (HCC)." (PMID 24743888, 2014). "In hepatocellular carcinoma (HCC), similar findings were demonstrated with increased CCR6+ Treg in the TME, which were inhibited with neutralizing mAb to CCL20." (PMID 31681327, 2019). "CCR6 impacts hepatocellular carcinoma (HCC) by recruiting Treg cells to the tumor site." (PMID 39000453, 2024). "Based on many previous reports, we suppose CCR6 may play major roles in hepatocellular carcinoma metastasis and participate in regulating the migration and invasion of HCC, and CCR6 expression would have some correlation with metastasis of HCC." (PMID 24743888, 2014).
melanoma (27 papers, 2010 to 2025). A malignant, usually aggressive tumor composed of atypical, neoplastic melanocytes. "In the past, it has been demonstrated that melanoma cell lines express the CCL20 receptor C-C chemokine receptor type 6 (CCR6) and that the tumor-associated macrophages (TAMs) are the main source of CCL20 expression." (PMID 38730689, 2024). "We have found that a low proportion of circulating effector memory CD8+CCR6+ T cells was associated with a better overall survival in stage IV melanoma." (PMID 30420855, 2018). "The IL-3 growth factor is able to upregulate CCR6 expression on human blood pDCs; however, it is so far undetermined whether IL-3 or other factors produced by cells of the TME are responsible for CCR6 upregulation by melanoma-associated pDCs." (PMID 39020402, 2024). "DNA vaccines containing a fusion of the gene encoding chemokine MIP-3α (CCL20), the ligand for CCR6 on immature dendritic cells (DCs), to melanoma-associated antigen genes have enhanced anti-tumor immunity and efficacy compared to those lacking the chemokine gene." (PMID 36741387, 2022). "Furthermore, tumour growth and vascularisation of B16F10-derived murine melanoma was dramatically inhibited in CCR6-deficient C57BL/6 mice in comparison with wild-type C57BL/6 mice." (PMID 32601464, 2020). "Moreover, given the negative prognostic value conveyed by tumor-infiltrating pDC in melanoma, CCR6 is likely to also be associated with poor patient outcome." (PMID 30420855, 2018). "Peripheral blood pDCs in stage I-III melanoma patients upregulated CCR6, a skin homing receptor, and were recruited to primary cutaneous melanoma lesions, in response to CCL20 produced in melanoma microenvironment." (PMID 39020402, 2024). "CCR6 is upregulated within lymph nodes, lung mucosa, and intestinal mucosa in patients with epithelial tumors and melanoma." (PMID 37182147, 2023). "This possibility is further supported by the activation of immune cells in the melanoma, which is believed to be supplemented by signals from CCR6-activated immune cells." (PMID 37182147, 2023). "Based on the correlation between CCR6 and melanoma incidence, we aimed to investigate the prognostic role of CCR6 and its relationship with immune infiltration in CM." (PMID 37182147, 2023). "Another issue that needs further research is the role of CCR6 in inflammation during the development of TME of melanoma." (PMID 37182147, 2023). "While circulating pDCs from healthy individuals expressed low levels of the chemokine receptor CCR6, the upregulation of its expression was observed in 36% of melanoma patients included in this study." (PMID 36232698, 2022). "For example, CXCR4 receptor is expressed in tumors such as ovary, glioma, melanoma and renal, CXCR6 in prostate cancer, CXCR2 in melanoma and CCR6 in colorectal and pancreatic cancer." (PMID 32499779, 2020). "T cell trafficking was further examined with CCR6 (MIP-3α receptor) and CXCR3 (IP-10/MIG/ITAC receptor) associated with intratumoral trafficking in melanoma." (PMID 31014399, 2019). "In melanoma patients, CCR6 was found to be more highly expressed on circulating plasmacytoid DC (pDC) than on pDC found in healthy volunteer controls." (PMID 30420855, 2018). "Elevated levels of CCR6 on blood PDCs were detected in melanoma patients and this concur with our findings." (PMID 20976171, 2010). "This study indicates the importance of CCL20/CCR6 axis for melanoma growth." (PMID 38786066, 2024). "Based on the correlation between CCR6 and melanoma incidence, we suggest that CCR6 has great potential as an independent prognostic predictor of clinical outcomes and may be important for diagnosing and preventing melanoma." (PMID 37182147, 2023). "Since our prognostic model is based on immune-related genes, the immune behavior of tumors is closely related to tumor stages; some information on melanoma stages may be needed to evaluate the relationship between CCR6 and immunity." (PMID 37182147, 2023).
melanoma (continued). "To confirm this, we knocked down CCR6 expression in melanoma cells and examined whether the effect of CCL20 on CM development was attenuated or eliminated." (PMID 37182147, 2023). "However, at this stage, we still believe that the CCR6 proposed in this research has the capacity to accurately predict the patients’ prognosis with melanoma and provide a new direction for new treatment strategies." (PMID 37182147, 2023). "The migration of pDCs to the TME could be directed through the CCL20/CCR6 axis, as proposed in melanoma patients." (PMID 36232698, 2022). "Moreover, IL-3 up-regulates the expression of chemokine receptor 6 (CCR6) in pDCs, as another mechanism for pDCs recruitment into the tumor microenvironment in melanoma, through CCR6/CCL20 (chemokine ligand 20) activation." (PMID 34737750, 2021). "Furthermore, Th17 cells have been shown to induce the production of CCL20 in tumor tissues, which recruits CCR6-expressing immature DCs to tumor tissues in a murine melanoma model." (PMID 34885241, 2021). "However, this needs to be explored further and to validated the prognostic value of CCR6+pDC in the melanoma tumor microenvironment." (PMID 30420855, 2018). "Importantly, CCR6 expression is detected on tumor cells from primary melanomas, lymph node, skin, colon, and brain metastases." (PMID 30420855, 2018). "The presence of CCR6+ pDC have been detected in primary melanoma tumors." (PMID 30420855, 2018). "Consistent with the observation that activation induces downmodulation of CCR6 expression, Ccr6-deficiency did not affect γδT17 cell infiltration of B16 melanomas, nor recruitment to the CNS during EAE onset." (PMID 28580944, 2017). "In addition, the inflammatory response pathway was found to be enriched in MES samples as compared to MEL, accompanied by significantly high expression of CXCL1 and its receptor, CXCR2, as well as chemokine receptors CCR4 and CCR6, in melanomas characterised by the invasive gene signature." (PMID 36765773, 2023). "Thus, further studies are required to understand the impact of tumoral CCR6 expression in metastatic dissemination and how this chemokine receptor might influence melanoma outcome." (PMID 30420855, 2018). "B16 melanoma, engineered to overexpress CCL20, grew slowly in CCR6 knockout mice compared to WT mice, with fewer leukocytes that infiltrated into the melanoma in the absence of CCR6." (PMID 38786066, 2024). "Metacluster C58748 represented CD4+CD45RO+ T cells that expressed CCR6, CCR7, CXCR3 and CXCR5 suggesting TFH cells in melanoma which exhibit elevated CEACAM1 levels in the context of treatment-resistant compared to treatment-naive disease." (PMID 38956268, 2024). "In melanoma, the profiling of GPCRs expressed by plasmacytoid DCs (pDCs) showed that the only significantly elevated GPCR is CCR6, which mediates the recruitment of pDCs from blood by the chemokine ligand CCL20 produced by melanoma cells." (PMID 25110692, 2014). "CCL20 is expressed by keratinocytes in the skin and by melanoma cells, suggesting that the CCL20/CCR6 interaction is involved in the pDC migration process from the blood to the tumor." (PMID 24282405, 2013). "Blood samples from patients with metastatic carcinoma (MC) or melanoma (MM) were enriched for CTC and expression of CR (CXCR4, CCR6, CCR7 and CCR9) was evaluated by flow cytometry." (PMID 22433180, 2012). "CCR6+ ILC3s in the spleen, when stimulated with IL-12, upregulate chemokine receptors such as CCR2, CCR6, CCR7, and CXCR5, leading to increased infiltration of CD8+ T cells, NK cells, NKT cells, and myeloid cells into B16 melanoma tumors." (PMID 40963622, 2025). "Additionally, the interaction between CCR6 and CCL20, which plays a decisive role in melanoma pathogenesis beyond chemoattraction, is considered to be important for CM development." (PMID 37182147, 2023).
melanoma (continued). "We previously reported that in human melanoma the chemokine axis CCR6/CCL20 is involved in a cooperative paracrine loop between CCR6 expressing tumor cells and CCL20 secreted by nontumoral cells in the stroma." (PMID 34439098, 2021). "Circulating pDCs from patients with melanoma have been found to express higher amounts of CCR6 and CXCR4, while their corresponding ligands CCL20 and CXCL12 are expressed on melanoma cells, suggesting that the CCR6/CCL20 and CXCR4/CXCL12 axes promote pDC migration from blood to melanoma foci." (PMID 29085361, 2017). "The ability of CCR6-expressing pDCs to migrate in response to CCL20 was demonstrated in transwell migration assays, suggesting that CCL20 produced in the TME might participate in recruiting CCR6-expressing pDCs in melanoma tumors." (PMID 36232698, 2022). "Thus, CCR2, but not CCR6, drives activated γδT17 cell migration to inflammatory sites during B16 melanoma and EAE." (PMID 28580944, 2017). "Very recently, a distinct subset of proinflammatory CLA+, CCR6+ Vγ9Vδ2 T cells has been described which is rapidly recruited from the blood to the skin compartment, but we do not have evidence if the Vγ9Vδ2 T cells which infiltrate melanoma belong to this novel γδ T cell subset." (PMID 23189169, 2012).